MYB (MYB proto-oncogene, transcription factor)
Diseases named in the same sentence as MYB in open-access papers (continued):
Sharing a sentence is not in itself a finding about the gene and the disease.
breast carcinoma (continued). "Glucuronidation of fulvestrant and the aromatase inhibitor anastrozole occurs via the UDP-glucuronosyltransferase 1A4 (UGT1A4), which was upregulated by fulvestrant in breast cancer cells via MYB." (PMID 38835346, 2024). "Although increased MYB levels promote breast cancer cell proliferation, the role of MYB in breast cancer is more complex and apparently context-dependent, with differences between proliferation and metastasis stages." (PMID 38835346, 2024). "The expression of various miRNAs was modulated (e.g., miR-34c-3p and miR-195-5p were downregulated) in trastuzumab-resistant breast cancer cells and in the plasma of trastuzumab-resistant cancer patients, which led to significantly increased MYB levels." (PMID 38835346, 2024). "In the immune cell types and in breast cancer, the pattern of the enhancer near the MYB transcription start site (TSS) is complex." (PMID 36688700, 2023). "The breast cancer-associated enhancer 6 kb from the TSS is bound by ESR1, consistent with the observation that MYB is regulated by the Estrogen Receptor." (PMID 36688700, 2023). "Originally, miR-193b-3p was reported to be a tumor suppressor inhibiting several tumor-associated proteins, including the MYB oncogene in T-cell acute lymphoblastic leukemia and MORC4 in breast cancer." (PMID 36860299, 2023). "In breast cancer, MYB acts as a promoter of breast cancer metastasis via activating the Wnt/β-catenin/Axin2 signaling pathway." (PMID 36994664, 2023). "MYB gene amplification and overexpression have been observed in acute myeloid leukemia, non-Hodgkin lymphoma, colorectal cancer, and breast cancer." (PMID 37468105, 2023). "Increased MYB expression confers resistance to tamoxifen in ER+ breast cancer cells by promoting EMT." (PMID 37813891, 2023). "In breast cancer, MYB regulates the response of DNA damage, suggesting a potential therapeutic target in ER+ breast cancer and possibly other cancer types via DNA damage response/repair pathways." (PMID 36994664, 2023). "MYB, a transcriptional activator, is a proto-oncogene that has been shown to be over-expressed in hematologic, colorectal, and breast cancer." (PMID 35525914, 2022). "SALL2 is a putative target gene of MYB, a transcription factor predicted as a prognostic gene signature across molecular breast cancer subtypes." (PMID 34944911, 2021). "Bioinformatics-based prediction revealed that MYB is a target gene of miR-187-5p, consistent with the reports that MYB functions as an oncogene in different tumours, including breast cancer." (PMID 35096852, 2021). "In recent years, some studies have shown that miR-200 regulates the development of breast cancer by directly negatively regulating the expression of MYB." (PMID 34876130, 2021). "MYBL2 (MYB proto-oncogene like 2) is included in the family of MYB transcription factors and was overexpressed in breast cancer." (PMID 34093635, 2021). "More importantly, MYB is involved in regulating the proliferation and apoptosis of breast cancer cells." (PMID 34876130, 2021). "Several in vitro and in vivo studies, carried out by our group, clearly demonstrated that the c-MYB expression is absolutely required for the proliferation of breast cancer." (PMID 36046384, 2020). "A three- to five-fold increase in repression of MYB was observed after combination, thus providing another basis for its use in the treatment of advanced breast cancer." (PMID 31527453, 2019). "This is functionally highly significant, as MYB silencing blocks estrogen-dependent breast cancer cell proliferation." (PMID 30833639, 2019). "Overall, the MYB/TAM multigene predictor can significantly separate low- and high-risk groups in the Breast Cancer Meta-base (n = 1888) and in all remaining datasets (n = 19) that monitor recurrence/relapse/metastasis events." (PMID 31406165, 2019). "We also report two cases of ACC of the breast, a rare tumor known to be a basal-like subtype of breast carcinoma with overexpression of C-kit and MYB protein." (PMID 30189404, 2018).
breast carcinoma (continued). "We have shown in breast cancer cells that suppression of proliferation by EMT is mediated at least in part through ZEB1 repression of MYB, a gene important in driving proliferation of estrogen receptor (ER)-positive primary breast cancers." (PMID 28750639, 2017). "It has been known for some time that MYB is highly expressed in estrogen receptor-positive (ER+ve) breast cancer, which reflects the fact that MYB is a direct target of estrogen/ER signaling (ER)." (PMID 26812885, 2016). "We have also shown that MYB expression in ER+ve breast cancer cells is regulated at the level of transcriptional elongation and as such, is suppressed by CDK9i." (PMID 26812885, 2016). "In the present study we used additional CDK9i AT7519 and BE-09-LN53, and confirmed that these have similar effects on MYB transcription, and also selectively induce apoptosis in ER+ve/MYB+ve breast cancer cells." (PMID 26812885, 2016). "We show that CDK9i can induce apoptosis and inhibit proliferation of ER+ve/MYB+ve breast cancer cells, while MYB−ve breast cancer cells are much less sensitive to these compounds." (PMID 26812885, 2016). "Our data also highlight the potential for development and use of these compounds, including highly selective CDK9i, in treating ER+ve breast cancer through concurrent inhibition of MYB, MCL-1 and other regulators of apoptosis." (PMID 26812885, 2016). "We have addressed this in part by showing that ectopic MYB expression can overcome the heightened sensitivity of in ER+ve/MYB+ve breast cancer cells (compared to MYB−ve cells) to CDK9i." (PMID 26812885, 2016). "A number of CDK9 inhibitors (CDK9i) are available and in breast cancer cells, such inhibitors can re-impose the block to MYB transcriptional elongation and suppress MYB expression." (PMID 26812885, 2016). "Here we examined the effects of CDK9i on breast cancer cells and the involvement of MYB in these effects." (PMID 26812885, 2016). "Here we have examined, in the present report, the potential of CDK9i to suppress the proliferation and/or viability of ER+ve breast cancer cells through the inhibition of MYB expression." (PMID 26812885, 2016). "More recently our laboratories have shown that MYB is required for the proliferation of breast cancer cells, contributes to suppression of apoptosis and differentiation, and is involved in the modulation of epithelial-mesenchymal transition." (PMID 26812885, 2016). "Our present data together with our previously-published data, show the activity of CDK9i against ER+ve/MYB+ve breast cancer cells and provide a mechanistic basis for this activity." (PMID 26812885, 2016). "MYB is essential for the proliferation of ERα positive breast cancer cells and is required for mammary carcinogenesis in murine models." (PMID 25853889, 2015). "We have shown that MYB drives proliferation and suppresses apoptosis and differentiation in estrogen receptor (ER)-positive breast cancer cells in response to estrogen, and that it is essential for mammary carcinogenesis in xenograft and transgenic models." (PMID 24283570, 2013). "Collectively our data link the transcriptional regulation of MYB by ZEB1 to the proliferative state of cells during EMT-MET in breast cancer, and also indicate a contribution of MYB to the epithelial phenotype." (PMID 24283570, 2013). "Analysis of publically available expression data from 51 human breast cancer cell lines that clustered into Luminal, BasalA, and BasalB subgroups also revealed significantly higher MYB expression in Luminal and Basal A subgroups compared with Basal B." (PMID 24283570, 2013). "Here we have identified an inverse relation between ZEB1 and MYB throughout these cell states, and also in the breast cancer cell lines MDA-MB-231 and MDA-MB-468." (PMID 24283570, 2013). "The current study sought to determine the ZEB1/MYB/proliferation interplay in the epidermal growth factor (EGF)-responsive PMC42 model of breast cancer EMT." (PMID 24283570, 2013).
breast carcinoma (continued). "PAX6 has also been implicated in promoting the proliferation of breast cancer cells, and we have reported that PAX6 is a direct MYB target gene in the neurogenic zones of the brain." (PMID 24283570, 2013). "We have confirmed that, like some other cancer cells, mammary carcinoma cells can be induced to differentiate and shown that MYB expression decreases during this process." (PMID 20659323, 2010). "This study has shown that MYB knockdown sensitizes breast cancer cells to induced differentiation and apoptosis." (PMID 20659323, 2010). "We found that MYB expression decreases following chemically-induced differentiation of the human breast cancer cell line MCF-7, and hormonally-induced differentiation of a non-tumorigenic murine mammary epithelial cell (MEC) line, HC11." (PMID 20659323, 2010). "We also found that shRNA-mediated MYB knockdown initiated differentiation of breast cancer cells, and greatly sensitised them to the differentiative and pro-apoptotic effects of differentiation-inducing agents (DIAs)." (PMID 20659323, 2010). "A functional role for MYB in MEC differentiation is implied by the effects of MYB knockdown on breast cancer cell lines." (PMID 20659323, 2010). "We recently demonstrated that MYB is essential for the proliferation of ER + ve breast cancer cells, and have now investigated its role in mammary epithelial differentiation." (PMID 20659323, 2010). "BCL2 suppresses apoptosis via the intrinsic pathway, and thus regulation of BCL2 is a plausible mechanism for the anti-apoptotic function of MYB in mammary carcinoma cells." (PMID 20659323, 2010). "To further understand the function of MYB in breast cancer and in mammary epithelial cells (MECs) generally, we have now investigated its role in the differentiation of these cells." (PMID 20659323, 2010). "We have found that mammary carcinoma cell lines in which MYB expression was 'knocked-down' by shRNA show changes that indicate differentiation has occurred in some of these cells." (PMID 20659323, 2010). "Sensitisation to the pro-apoptotic effects DIAs is mediated by decreased expression of BCL2, which we show here is a direct MYB target in breast cancer cells." (PMID 20659323, 2010). "Nevertheless, it has been shown that MYB is expressed at relatively high levels in estrogen receptor (ER) positive breast cancers and tumor cell lines." (PMID 20659323, 2010). "Our data (and that reported here) imply that MYB is required in ER positive mammary carcinoma cells for three key 'hallmarks of cancer' - continued proliferation, suppression of differentiation, and resistance to apoptosis." (PMID 20659323, 2010). "In addition, cyclin D1 was overexpressed in tamoxifen-resistant breast cancer cells with upregulated MYB." (PMID 38835346, 2024). "The oncogenic connection of MYB with COX-2 was also described for inflammation-driven breast cancers, which might be sensitive to a combined PIK3 inhibitor and COX-2 inhibitor therapy." (PMID 38835346, 2024). "The protein kinase C (PKC) inhibitor sotrastaurin was active against ER-positive T-47D luminal breast cancer cells by downregulation of the ER effector MYB, suggesting a promising role of MYB inhibition in the prevention and treatment of tamoxifen-resistant ER-positive breast cancers." (PMID 38835346, 2024). "The investigation of the gene expression profile of fulvestrant-resistant breast cancer cells induced by zinc finger transcription factors revealed four gene clusters that overlapped with MYB-regulated genes, indicating a vital role of MYB in fulvestrant resistance." (PMID 38835346, 2024). "In some breast cancers, expression of MYB is enhanced by the presence of another transcription factor, oestrogen receptor alpha (ERα), where a ligand–ERα complex is required to alleviate attenuated expression of MYB." (PMID 34638473, 2021). "In breast cancer, MYB induces EMT and significantly increases tamoxifen resistance." (PMID 34876130, 2021).
breast carcinoma (continued). "In breast cancer, it has also been reported that miR-200b may affect breast cancer cells’ response to tamoxifen, involving MYB." (PMID 33806327, 2021). "Interestingly, CRYBMIM also exhibited anti-tumor effects on various solid tumor cell lines, including some medulloblastoma, neuroblastoma, and breast carcinoma cells, at least some of which also exhibit high levels of MYB expression and genetic dependence." (PMID 33527899, 2021). "Estrogen positive breast cancer cells were found to be very sensitive to CDK9 inhibitors and at a sub-nanomolar concentration of CDK9 inhibitor, the cell undergoes apoptosis associated with a several-fold downregulation of c-MYB expression." (PMID 36046384, 2020). "Our findings identify a novel role for p95HER2-specific miRNA changes in distinguishing p95HER2 positive cancers from those overexpressing only HER2, and uncover a signaling axis from miR-221/222 and -503 over MYB proteins to TIMP2 important for controlling cell motility in breast cancer." (PMID 30833639, 2019). "However, our work on the regulation of MYB expression in breast cancer has suggested an alternate approach to suppress MYB activity." (PMID 26812885, 2016). "Furthermore ectopic MYB expression can protect ER+ve breast cancer cells against CDK9i, suggesting that the effects of the latter are at least partly due to MYB down-regulation." (PMID 26812885, 2016). "Therefore, we conclude that maintenance of MYB expression can overcome the sensitivity of MCF-7 cells to CDK9i, which is in turn consistent with MYB down-regulation being a primary mediator of ER+veMYB+ve breast cancer cell killing by this class of drugs." (PMID 26812885, 2016). "Furthermore, high levels of MYB mRNA and protein expression were detected in various solid tumors, such as colorectal and breast cancers." (PMID 27533466, 2016). "Since we previously showed that MYB expression is essential for proliferation and contributes to survival of ER+veMYB+ve breast cancer cells, we wanted to investigate the effect of CDK9i on the proliferation and viability of a panel of breast cancer cell lines." (PMID 26812885, 2016). "Moreover, ectopic expression of MYB was sufficient to suppress CDK9 inhibitor-mediated apoptosis, strongly supporting the notion that MYB is a critical target of these inhibitors in ER+ve breast cancer cells." (PMID 26812885, 2016). "Importantly we also demonstrated that MYB is required for mammary tumour formation and/or progression in mouse models, and is frequently upregulated in metastases." (PMID 26812885, 2016). "Furthermore, MYB expression in breast cancer cells is regulated by a similar mechanism, whereby attenuation is overcome by estrogen receptor binding." (PMID 25853889, 2015). "Most importantly, MYB suppresses the differentiation and apoptosis of human breast cancer cells." (PMID 23935942, 2013). "We studied the interplay between EMT and proliferation control by MYB in breast cancer cells." (PMID 24283570, 2013). "The Raschella group initially reported that MYB expression was upregulated in ER-positive human breast cancer cell lines after TGF-β treatment because of transcriptional activation, release of miR-200 family suppression, and protein stabilization, and was instrumental in promoting EMT effects." (PMID 24283570, 2013). "MYB amplification has been found at high frequencies in human hereditary breast cancer." (PMID 24098698, 2013). "Furthermore, we have established a functional and reciprocal relation between ZEB1 and MYB that is prevalent in breast cancer systems." (PMID 24283570, 2013). "Moreover we, and others have previously shown that MYB is a direct target of estrogen/ER signaling, and that MYB expression in breast cancer cells is regulated by transcriptional attenuation within its first intron." (PMID 20659323, 2010). "To determine whether MYB acts directly on the BCL2 gene in breast cancer cells, we performed ChIP assays using MCF-7 cells." (PMID 20659323, 2010).
breast carcinoma (continued). "As MYB knockdown in mammary carcinoma cells resulted in only a limited amount of differentiation, we next asked whether MYB knockdown was able to act in a synergistic manner with DIAs." (PMID 20659323, 2010). "Finally, our observation that DIAs and MYB inhibition synergize in killing breast tumor cells suggests an approach to developing new treatments for ER/MYB positive breast cancer." (PMID 20659323, 2010). "Their results suggested that MYB may act as a coactivator for Stat5a, and also supported a proliferative function for MYB in human breast cancer." (PMID 20659323, 2010). "Although we have discussed a number of approaches to targeting MYB itself in breast cancer, it may instead be possible to target specifically the anti-apoptotic effectors of MYB to induce tumor cell killing by DIAs." (PMID 20659323, 2010). "This could potentially make MYB an excellent therapeutic target in breast cancer, particularly under conditions where MYB activity is limiting for one or more of these processes." (PMID 20659323, 2010). "Indeed we have shown here that BCL2, a known MYB target gene in other cell types, is directly regulated by MYB in breast cancer cells, and have identified multiple MBS within the BCL2 gene." (PMID 20659323, 2010). "Thus these data show that MYB knockdown sensitizes mammary carcinoma cells to differentiation and, at high concentrations of DIA, to apoptotic death." (PMID 20659323, 2010). "Therefore, deregulated expression of MYB could be used as an indicator to predict the response to drug therapy for breast cancer patients." (PMID 37813891, 2023). "Moreover, sporadic MYB amplifications, which have been reported in BRCA1 positive tumors, may further contribute to the overall high levels of MYB expression in patients with breast cancer." (PMID 27533466, 2016). "Since MYB is not known to be involved in breast cancer, we could argue that each mutation with a high PRIME score for the MYB model would be a false positive prediction." (PMID 26562774, 2015). "Moreover, our findings suggest MYB may be a viable therapeutic target in breast cancer and suggest specific approaches for exploiting this possibility." (PMID 20659323, 2010). "Therefore, we asked whether the level of MYB would also be reduced when mammary carcinoma cells underwent differentiation." (PMID 20659323, 2010). "Our observation that fulvestrant, which is in clinical use for breast cancer treatment, appears to substitute in this regard for MYB knockdown suggests that the combination of this agent with clinically acceptable DIAs might be one approach to bring this approach to clinical application." (PMID 20659323, 2010). "In breast carcinoma tissue with overexpression of the HER2 receptor, a high level of miRNA-221 was also found, and it was shown that it leads to reduced expression of MYB and MYBL1." (PMID 39408891, 2024). "More importantly, MYB and SALL2 were suggested to attenuate histological grade promotion and prevent breast cancer progression." (PMID 34944911, 2021). "These include the signaling gene TGFBR1, the proto-oncogene MYB as well as many immune-related genes such as CCR7 and FCRL3, reinforcing evidence for a role of immune components in influencing breast cancer patients’ prognosis." (PMID 28059167, 2017). "MYB and CDH1 gene expression were found to correlate in human breast cancer cell lines and in primary human breast tumors and metastases." (PMID 24283570, 2013). "We also report that a highly specific AHR agonist significantly (P < 0.05) inhibits the expression of E2F1, CCND1 (known as Cyclin D1), MYB, SRC, JAK2, and JUND in breast cancer cells." (PMID 24171117, 2013). "This is further supported by a positive correlation of MYB and CDH1 in breast cancer bone metastases, with both markers staining inversely to VIM (part ii)." (PMID 24283570, 2013).